RNU6-900P (RNA, U6 small nuclear 900, pseudogene)
Gene: Small nuclear RNA gene on chromosome 22 (37,891,347 to 37,891,448, forward strand). Ensembl gene ENSG00000207227.
Homologues: Orthologues: chimpanzee U6 (100% identical), mouse Gm25006 (81% identical), dog U6 (78% identical), guinea pig U6 (78% identical), dog U6 (75% identical), mouse Gm24504 (72% identical), rat LOC120099420 (72% identical), pig U6 (68% identical), rat LOC120098341 (68% identical). Paralogues in human: RNU6-140P (88% identical), RNU6-1124P (86% identical), RNU6-16P (86% identical), RNU6-246P (86% identical), RNU6-1056P (85% identical), RNU6-1094P (85% identical), RNU6-338P (85% identical), RNU6-35P (85% identical), RNU6-45P (85% identical), RNU6-536P (85% identical), RNU6-637P (85% identical), RNU6-1029P (84% identical), and 1287 more.